TNF (tumor necrosis factor)
Diseases named in the same sentence as TNF in open-access papers (continued):
Sharing a sentence is not in itself a finding about the gene and the disease.
cancer (continued). "Id1 has multiple oncogenic functions imparting resistance to TNFα and anti-cancer drug-induced apoptosis." (PMID 20565867, 2010). "Taken together, our study demonstrates that enhanced TNF-α induced apoptosis in HEK293T cells by over expression of miR-23a∼27a∼24-2 cluster provides new insights in the development of novel therapeutics for cancer." (PMID 19513126, 2009). "Our study shows that TNF-α plays a key role in the induction of TSS, and complete removal of TNF-α makes the mice more susceptible to diseases like cancer." (PMID 20041187, 2009). "The protein product, TNF-α, activates the nuclear factor kappa beta (NF-κB) transcription factor, and is critical for inflammatory and apoptotic responses in cancer progression." (PMID 19390683, 2009). "Although over 20 cytokines have been developed for the treatment of cancer, only IL-2, IFN-α and TNF-α have been approved in the US and/or Europe for immunologic anti-cancer therapy." (PMID 19175928, 2009). "This invasion was attenuated by anti-TNFα antibodies and demonstrates that cancer cells utilise surrounding cells to facilitate invasion of the surrounding extracellular matrix." (PMID 19014637, 2008). "Vasopressin, prostaglandin E2 and TNF-α have been proposed to be involved in the development of cancer cachexia in Walker-256 tumour-bearing rats." (PMID 18226207, 2008). "Both IL-6 and TNF-α levels were increased significantly in the TB group, which confirmed the role of TNF-α besides IL-6, in the pathogenesis of cancer cachexia in the C26 model." (PMID 19018259, 2008). "Tumor necrosis factor (TNF)-related apoptosis-inducing ligand (TRAIL) is an important member of the TNF superfamily with great potential in cancer therapy." (PMID 18946424, 2008). "The growth inhibition of keratinocytes induced by TNF-α and histamine was also confirmed under high-calcium conditions since carcinoma cells were also cultured in high-calcium medium." (PMID 18257926, 2008). "In order to induce cytolysis in these carcinoma cells by TNF-α, additional stressors are needed, such as protein synthesis inhibition or radiation." (PMID 18257926, 2008). "Nonetheless, this study suggests that mast cells contribute to both pain and bladder inflammation and pathophysiology through the divergent actions of histamine and TNF, respectively." (PMID 18461160, 2008). "Genes encoding proteins that promote Ca++ sensitization such as troponin T1 (skeletal slow), calmodulin, cam kinase, caldemon and TNF were also highly expressed in the carcinomas." (PMID 18811984, 2008). "Tumor necrosis factor-alpha activates both cell death and cell survival pathways, which render most cancer cells resistant to its cytotoxicity." (PMID 23675041, 2007). "Sulforaphane, a naturally occurring cancer chemopreventive agent found in broccoli, has been shown to suppress LPS-mediated expression of iNOS, Cox-2 and tumor necrosis factor-α (TNF-α) in Raw 264.7 macrophage cells." (PMID 17653053, 2007). "Cancer cells have demonstrated an increase in invasive capacity when exposed to recombinant MIF or co-cultured with macrophages leading to a TNF-α dependant increase in MIF expression via an NFκ-B pathway." (PMID 17650334, 2007). "IL-6, IL-8, IL-12, IL-13, IFN-γ, MCP-1, MIP-1β and TNF-α were significantly more abundant in carcinoma than in normal breast." (PMID 17261184, 2007). "On this respect, dexamethasone (Dex) dependent protection against TNF-alpha-mediated cell death in the MCF-7 cell line has been demonstrated to be a useful model for the study of this type of cancer." (PMID 16504042, 2006). "More recently, inappropriately expressed TNF was also shown to play a role in the development of cancer but in a more complex manner." (PMID 15026813, 2004).
cancer (continued). "We are currently conducting a phase I human clinical trial to evaluate the effect of blocking TNF by using TNF autovaccination in patients with a variety of cancers." (PMID 15026813, 2004). "TNF is a proinflammatory cytokine involved in the pathogenesis of chronic inflammatory diseases, but also in metastasis in certain types of cancer." (PMID 15026813, 2004). "The effect of the incubation of monocytes with MDA-MB231 cancer cells was also tested on TNF alpha, a cytokine secreted by monocytes." (PMID 12698185, 2003). "We demonstrated that TNF alpha secretion by monocytes was dramatically increased when incubated with MDA-MB231 cancer cells." (PMID 12698185, 2003). "TNF alpha-induced apoptosis of MDA-MB231 cancer cells was studied after incubation of cancer cells with TNF alpha at a concentration of 50 ng ml−1." (PMID 12698185, 2003). "This resistance is explained by constitutive activation of NF-KB in MDA-MB231 cancer cells, which prevents TNF alpha-induced apoptosis." (PMID 12698185, 2003). "Incubation of monocytes with MDA-MB231 cancer cells resulted in a downregulation in the secretion of the antiproliferative cytokine Oncostatin M, while the apoptotic factor TNF alpha was dramatically increased." (PMID 12698185, 2003). "When MDA-MB231 cancer cells were incubated with 50 ng ml−1 TNF alpha, less than 25% of cancer cells entered apoptosis (pre-G1 phase) only after a 72-h incubation." (PMID 12698185, 2003). "Tumour necrosis factor-α (TNF-α) is a cytokine that can induce cell death of different cancers via a cellular cascade of proteases, the caspases." (PMID 11044363, 2000). "mRNAs of cytokines, IFN-gamma and TNF-alpha, were detected by reverse transcription-polymerase chain reaction (RT-PCR) in both carcinoma and remote normal tissues." (PMID 8605101, 1996). "We have examined the effects of intravenous infusion of recombinant human tumour necrosis factor (rh-TNF) on serum activity of phospholipase A2 (PLA2) in patients with malignancies." (PMID 18475466, 1992). "Consequently, TNF‐α blockers targeting cancer cachexia and pain are being tested to improve patient quality of life." (PMID 41583906, 2026). "In specific cases, such as in patients with a history of cancer or with a tendency for Candida infections, antibodies targeting IL-23 might be a preferred choice over biologics targeting IL-17 or TNF." (PMID 40536951, 2026). "Additionally, inflammatory factors like TNF‐α and IL‐1β contribute to cancer pain by activating peripheral nerves." (PMID 41583906, 2026). "Kyoto Encyclopedia of Genes and Genomes (KEGG) enrichment analysis indicated that these genes were predominantly enriched in immune‐related pathways, including IL‐17 signaling, Toll‐like receptor signaling, TNF signaling, and the PD‐L1/PD‐1 checkpoint pathway in cancer." (PMID 41270217, 2026). "TNFAIP3, a key regulator of TNF‐α signaling, plays a dual role in cancer biology, but its precise function in BRCA pathogenesis and immune modulation remains unclear." (PMID 41461391, 2026). "TNF is recognized as a pivotal cytokine that is a bridge between inflammation and cancer." (PMID 40313970, 2025). "Circulating TNF-α is a master regulator of cancer-related inflammation." (PMID 41473193, 2025). "In fact, blocked TNFα (and therefore the impairment of its biological action) could prevent the cells of the immune system from detecting cancer cells." (PMID 41008635, 2025). "Fat cells secrete inflammatory mediators such as TNF-α and IL-6, which promote cancer induction." (PMID 40361337, 2025). "Nowadays, recombinant IL-2, IFN-α and TNF are applied into cancer immunotherapy." (PMID 41333471, 2025). "We further compared NE1 and NE2 cells, finding that NE1 retained relative activation of the AR signaling axis and enrichment in cancer-promoting signaling pathways such as TNF-α and TGF-β, whereas NE2 showed upregulation in oxidative phosphorylation and mitochondrial metabolism." (PMID 41041045, 2025).
cancer (continued). "Additionally, the UPP1 level is also positively correlated with the levels of TNF-α and IL-1β in most cancer types, consistent with our findings suggesting that both cytokines are required to upregulate UPP1." (PMID 41243973, 2025). "In 2022, an RCT published in The New England Journal of Medicine found that the incidence of cancers was higher with tofacitinib compared to tumor necrosis factor (TNF) inhibitors in patients with RA older than 50 years of age and had at least one additional cardiovascular risk factor." (PMID 40507276, 2025). "However, in colorectal cancer, TNF-α induces ILF3 expression, which stabilizes SLC3A2 mRNA, enhances cystine uptake and GSH synthesis, ultimately reducing cancer cell susceptibility to ferroptosis." (PMID 41450917, 2025). "More recently, a large study from Sweden and Denmark reported no increased cancer risk associated with TNF inhibitor use in patients with spondyloarthritis or psoriatic arthritis." (PMID 41302997, 2025). "While most studies report that TNF-α promotes tumorigenesis by stimulating growth, proliferation, invasion, metastasis, and angiogenesis, some experimental systems suggest an antitumor effect, noting its ability to induce cancer cell death." (PMID 39860614, 2025). "Elevated levels of pro-inflammatory cytokines, such as IL-6 and TNF-α, which are commonly observed in cancer cachexia, trigger STAT3 activation, leading to the transcription of genes that exacerbate systemic inflammation, accelerate muscle protein degradation, and disrupt lipid metabolism." (PMID 40704145, 2025). "Patients with infections or malignancies experience generalized weakness, which is induced by proinflammatory cytokines acting on the central nervous system, such as interleukin-1 (IL-1) and tumor necrosis factor (TNF)." (PMID 40709133, 2025). "This review explores the multifaceted role of CREPT in cancer, with a focus on its mechanistic role in key signaling pathways, such as its interaction with cell cycle regulators, Wnt/β-catenin, and the tumor necrosis factor (TNF) signaling pathway." (PMID 40723282, 2025). "Among these, IL-6 emerged as the most consistently and markedly increased marker, suggesting it may be a central mediator of cancer-induced neuroinflammation, followed by IL-1β and TNF-α." (PMID 41155372, 2025). "Transforming growth factor β (TGFβ) and tumor necrosis factor α (TNFα) stimulate transcription of the WWP1 gene via unknown mechanisms in cancer progression." (PMID 41009733, 2025). "Additionally, ten studies evaluated new cancer incidence: anti-TNF therapy RR was 1.02 (95% CI 0.70–1.50), and vedolizumab RR was 0.44 (95% CI 0.33–0.60)." (PMID 41228267, 2025). "A systematic review also implied that this cancer-enhancing crosstalk might be mediated by interleukin-6 (IL-6), tumor necrosis factor-alpha (TNF-alpha), vascular endothelial growth factor (VEGF), and other potential mechanisms waiting for exploration." (PMID 39875372, 2025). "Moreover, upregulation of the metal‐ion transporter ZRT‐ and IRT‐like protein 14 (ZIP14) has been shown in cachectic skeletal muscles of mice and in human patients with metastatic cancer in response to cancer‐induced TNF‐α and TGF‐β cytokine release." (PMID 40183240, 2025). "A meta-analysis including 11,679 cancer survivors, of whom 3707 were treated with anti-TNF agents post-cancer diagnosis, reported no increased risk of cancer recurrence compared to unexposed individuals." (PMID 41228267, 2025). "Deep anesthesia may impact cancer growth by a depression of NK cells, ultimately reducing T-cells and killer cell activities as well as a decreased production of TNFα and IFN y." (PMID 40097954, 2025). "It has been reported that adiponectin can suppress cancer development by inhibiting TNF-α." (PMID 39980561, 2025).
cancer (continued). "By releasing cytokines that promote inflammation such as Interleukin (IL)-12, IL-23, and tumor necrosis factor (TNF)-α, as well as nitric oxide (NO), these macrophages contribute to activate immune system by preventing the growth and proliferation of cancer cells." (PMID 40352926, 2025). "Furthermore, U11 exhibited marked upregulation of TNF-α-induced NF-κB signaling, a pathway known to enhance cancer cell invasiveness and metastatic potential." (PMID 40948800, 2025). "In addition, previous studies have indicated that IL‐8, IL‐6 and TNF‐α are cytotoxic mediators of the link between inflammation and cancer." (PMID 40289540, 2025). "In Taiwan, nationwide registry studies comparing patients with AS to the general population reported that AS itself was associated with increased cancer risk; however, patients treated with TNF inhibitors were not analyzed separately." (PMID 41302997, 2025). "Additionally, KEGG pathway enrichment analysis highlighted 88 enriched pathways, including the PI3K-AKT signaling pathway, MicroRNAs in cancer, IL-17 signaling pathway, and TNF signaling pathway." (PMID 41471291, 2025). "The spread of cancer cells may be prevented by vitamin K through the reduction in inflammation (for example, by decreasing IL-6 and TNF-α)." (PMID 41003423, 2025). "In these models, TNF inhibition improves both cancer survival and immune-related toxicity." (PMID 40774545, 2025). "The inhibitory effect of Phen on TNF-mediated necroptosis was also evident in another human cancer cell line, an ectopic RIPK3-expressing MDA-MB231 cell line, as well as in murine MC-38 cells and MEFs, expanding this observation to multiple cell types and species." (PMID 40456737, 2025). "Another active pathway involved in the pathogenesis of cancer cachexia is the TNF-α/NF-κB pathway." (PMID 40869331, 2025). "Notably, tumor necrosis factor-α (TNF-α) and IL-6 frequently establish a positive feedback loop that drives cancer progression." (PMID 40149421, 2025). "This gene’s activity in the TNF signaling pathway further supports inflammation, which is common to both metabolic and cancerous diseases, emphasizing its role in fostering an environment that enables cancer cell migration and metastasis." (PMID 40127075, 2025). "Furthermore, a review highlights that tumor necrosis factor‐alpha (TNF‐α) strongly promotes cancer progression and metastasis, highlighting the role of inflammatory cytokines in cancer." (PMID 40095296, 2025). "One reason might be that TNF-α is a double-edged sword: completely blocking TNF-α carries risks, and TNF-α-directed treatments could have complex effects on the immune response to cancer." (PMID 41007766, 2025). "In a subgroup analysis focused on patients with IBD, no increased risk of new or recurrent cancer was observed following exposure to TNF-α antagonists, with an incidence rate ratio (IRR) of 0.68 (95% CI: 0.40–1.16)." (PMID 40227584, 2025). "culture filtrate extract significantly reduced TNF-α production in MCF-7 cancer cells." (PMID 40624613, 2025). "In this regard, although the anti-inflammatory effect of ITF3756 on the TNF-α signaling pathway could be seen as a disadvantage for certain aspects of cancer therapy, in the context of immune checkpoint therapy combinations it could be helpful and relevant." (PMID 40433358, 2025). "However, new studies are being carried out to answer these questions that remain of interest, mainly in high-risk groups for disease activation, such as patients living with HIV, or cancer, and those using anti-TNF biological treatment." (PMID 40190751, 2025). "When comparing to TNF- mRNA, miR-21 was found to be more abundant in cancer cells." (PMID 41476448, 2025). "Additionally, TNF-α, a known promoter of cancer cell proliferation, was found to significantly increase the cell viability of HN13 and HSC-4 cells." (PMID 40444012, 2025).
cancer (continued). "Notably, the significant differences between mock-treated and PDS-0330-treated GIST cells were also associated with metabolism, cancer, MAPK, AKT, and TNF signaling." (PMID 40943068, 2025). "Similarly, a retrospective American study involving 184 IBD patients with a prior history of cancer reported an incidence of new or recurrent cancer of 4.2 per 1000 person-years among those exposed to TNF-α antagonists." (PMID 40227584, 2025). "Roburic acid (RA), a tetracyclic triterpenoid, has been identified as a substance capable of inhibiting key NF-κB and MAPK signaling pathways through direct interaction with TNF-α, as well as preventing the production of inflammatory mediators and cancer progression." (PMID 40650205, 2025). "A few patients mentioned concerns about RA drug effects on cancer or had heard about the link between two tumor necrosis factor inhibitors, etanercept and adalimumab, and cancer, and a few patients mentioned concerns about steroids related to immunosuppression." (PMID 40598674, 2025). "In BHT, TBHQ binds to TNF and other factors to activate the TNF signaling pathway, which leads to hepatotoxicity, nephrotoxicity, and neurotoxicity and further leads to the development of cancer." (PMID 40238193, 2025). "Dietary vitamin K (phylloquinone) consumption has been documented to have an inhibitory effect on systemic inflammation by reducing the level of pro-inflammatory cytokines, particularly tumor necrosis factor-α and interleukin-6, a well-known factor for promoting the onset and development of cancer." (PMID 41003423, 2025). "TNF-α is a pleiotropic cytokine identified as a major regulator of inflammatory responses, while NF-κB is a key transcription regulator of immune responses, inflammation, and cancer." (PMID 41303449, 2025). "Moreover, high FUT1 expression had a significant impact on estrogen response, KRAS signaling, and TNF-α signaling via NF-κB pathways in most cancer types." (PMID 40084262, 2025). "Therefore, targeting the TNF/TNFR2 signaling pathway has been considered a promising strategy in cancer immunotherapy." (PMID 40141200, 2025). "Anti-TNF therapies could reduce inflammation, benefiting patients with both metabolic disorders and cancer." (PMID 40547917, 2025). "For instance, luteolin-induced ROS accumulation plays a key role in suppressing the nuclear transcription factor NF-κB and enhancing Jun N-terminal kinase (JNK) activation, thereby sensitizing cancer cells to tumor necrosis factor-alpha (TNF-α)-induced apoptosis." (PMID 41304905, 2025). "EGCG exerts anti-cancer activity by targeting multiple cellular processes, such as oxidative stress reduction, and suppression of inflammatory mediators like Interleukin-6 (IL-6) and Tumor Necrosis Factor-α (TNF-α)." (PMID 40918466, 2025). "Also, due to the widespread expression of TNFR1 across various cell lines, the selectivity of TNF-based cancer therapy is limited." (PMID 40597922, 2025). "The TNF-α gene’s promoter region (− 308) has a G-to-A substitution (TNF-α−308G > A), which increases TNF-α expression and is linked to several illnesses, including hepatocellular and other cancers." (PMID 39570546, 2025). "TNF signalling has already been reported to regulate radiosensitivity in several cancer cell lines." (PMID 40792276, 2025). "LNCSEA 2.0 annotation analysis predicts the interaction of several lncRNAs, suggesting that they are deeply related to multiple cancer immunology signaling pathways that may act as modulators in the TNF signaling pathway." (PMID 41440381, 2025). "Additionally, cytokines such as IL-6, IL-1β, and TNF-α, play important roles in cancer initiation, growth, and metastasis development." (PMID 40699634, 2025). "In the medical condition subgroups, a significant decrease in TNF-α levels was observed in the cancer (SMD = −0.66; 95% CI, −2.42 to 1.11) and MD (SMD = −0.66; 95% CI, −1.61 to 0.30) groups, but only a slight decrease was observed in the CNS group (SMD = −0.10; 95% CI, −0.34 to 0.13)." (PMID 40281902, 2025).